IL10RB (interleukin 10 receptor subunit beta)
Diseases named in the same sentence as IL10RB in open-access papers (continued):
Sharing a sentence is not in itself a finding about the gene and the disease.
malaria (1 paper, 2013). Malaria is a serious and sometimes fatal disease caused by a parasite that commonly infects a certain type of mosquito which feeds on humans. "Recently combined promoter haplotypes of the IL10RA and IL10RB genes have been shown to be associated with protection against severe malaria in Gabonese children." (PMID 23297791, 2013). "To summarize, selected regulatory SNPs in the promoter region of FOXP3, IL10RA, IL10RB, STAT6 and TNFRSF18 genes have been investigated for possible association with uncomplicated malaria and high P. falciparum parasite density among Congolese children." (PMID 23297791, 2013).
Multiple Organ Failure (1 paper, 2021). A progressive condition usually characterized by combined failure of several organs such as the lungs, liver, kidney, along with some clotting mechanisms, usually postinjury or postoperative. "Multiple organ failure observed in the patient presented could be related to the triple gene dose of four interferon receptors (IFNAR1, IFNAR2, IFNGR2, and IL10RB) located at 21q22.11." (PMID 34760326, 2021).
myeloid leukemia (1 paper, 2021). A clonal proliferation of myeloid cells and their precursors in the bone marrow, peripheral blood, and spleen. "The MFI of IL-10RA ranged from 1702 to 3372 and that of IL-10RB from 3977 to 13126 in five myeloid leukemia cell lines (MV4-11, Kasumi-1, U937, Thp-1 and Molm-13)." (PMID 34392305, 2021).
myocardial infarction (1 paper, 2024). Gross necrosis of the myocardium, as a result of interruption of the blood supply to the area, as in coronary thrombosis. "Five proteins deregulated in homozygous LAV-BPIFB4 carriers (e.g. CXCL11, CSF-1, SLAMF7, IL-10RB and TNFRSF9) emerged from a recent proteome-based CV risk model as the top factors predicting myocardial infarction event." (PMID 38468336, 2024).
myocarditis (1 paper, 2025). Myocarditis is a condition that is characterized by inflammation of the heart muscle (myocardium). "Although ICAM1 and IL10RB have anti-inflammatory effects, they exhibit pro-inflammatory effects in a variety of diseases, which may be unfavorable for myocarditis." (PMID 40906170, 2025).
osteonecrosis (1 paper, 2025). A none disease characterized by death of bone tissue due to a lack of blood supply. "On the other hand, 3 cytokines showed a negative causal effect on osteonecrosis, suggesting a decreased risk: MCP-4 (IVW OR = 0.81, 95% CI = 0.67–0.99, P = .038), IL-10RB (IVW OR = 0.84, 95% CI = 0.699–0.999, P = .049), and CSF1 (IVW OR = 0.72, 95% CI = 0.54–0.96, P = .026)." (PMID 40760551, 2025).
osteosarcoma (1 paper, 2021). A usually aggressive malignant bone-forming mesenchymal neoplasm, predominantly affecting adolescents and young adults. "In the Kaplan–Meier curves for single genes, the expression of AL391121.1 and UNC5B.AS1 was negatively correlated with prognosis of osteosarcoma patients, whereas the expression of AC090559.1, and IL10RB.DT was positively correlated." (PMID 34513835, 2021).
periodontitis (1 paper, 2020). An acute or chronic inflammatory process that affects the tissues that surround and support the teeth. "Increased IL10RB expression have been found to be associated with cardiovascular diseases in older heart patients withstroke and in patients with DS affected by periodontitis." (PMID 33260695, 2020).
prostate carcinoma (1 paper, 2024). A carcinoma that arises from epithelial cells of the prostate gland. "The Weighted mode method suggested a potential causal association between Interleukin-10 receptor subunit beta and prostate cancer (OR: 0.93, 95% CI: 0.90–0.97, P = 0.001, PFDR = 0.09)." (PMID 38874503, 2024). "However, after adjusting for the false discovery rate, the Weighted median method showed that Interleukin-10 receptor subunit beta was associated with a lower risk of prostate cancer (OR: 0.93, 95% CI: 0.90–0.97, P < 0.001, PFDR = 0.03)." (PMID 38874503, 2024). "The MR results using the IVW method showed two factors that were protective against prostate cancer: CUB domain-containing protein 1 (OR: 0.95, 95% CI: 0.91–0.99, P = 0.015) and Interleukin-10 receptor subunit beta (OR: 0.95, 95% CI: 0.91–0.98, P = 0.005)." (PMID 38874503, 2024). "For prostate cancer, CUB domain-containing protein 1 and Interleukin-10 receptor subunit beta were found to be protective, while Glial cell line-derived neurotrophic factor and SIR2-like protein 2 were identified as risk factors." (PMID 38874503, 2024).
psoriasis (1 paper, 2020). An autoimmune condition characterized by red, well-delineated plaques with silvery scales that are usually on the extensor surfaces and scalp. "IL-26 was expressed in psoriasis patients in combination with the IL-26 receptor, IL-10RB, and IL-20RA expressed by keratinocytes." (PMID 32290250, 2020).
testicular germ cell tumor (1 paper, 2022). A germ cell tumor arising from the testis. "Additionally, UPF3B expression was positively correlated with most immunoinhibitors, including TGFBR1, IL10RB, CD160, CD274, TIGIT and PDCD1 in UVM, OV, KIHC, and LIHC, but negatively associated with the expression of majority genes in STAD and Testicular Germ Cell Tumors (TGCT)." (PMID 36194583, 2022).
thymic tumors (1 paper, 2024). "In conclusion, this study provides genetic evidence supporting the causal protective effect of physical activity on thymic tumors, with IL10RB partially mediating this relationship." (PMID 39769247, 2024). "In conclusion, physical activity causally reduces the risk of thymic tumors, partially mediated by IL10RB, highlighting its potential role in cancer prevention through immunomodulation." (PMID 39769247, 2024). "Furthermore, our two-step MR mediation analysis indicated that IL10RB may partially mediate this protective effect, suggesting a potential immunomodulatory pathway through which physical activity influences thymic tumor risk." (PMID 39769247, 2024). "The partial mediation by IL10RB indicates that while physical activity exerts a direct protective effect against thymic tumors, a portion of this effect is mediated through alterations in cytokine signaling." (PMID 39769247, 2024).
tumor (28 papers, 2011 to 2025). "In summary, biomarkers associated with both oncogenic (ITGAV, CEACAM1, CXCL1, IL-10RB) and tumor-suppressive actions (CEACAM1) were found to increase the diagnostic performance of HE4, CA125 and age in our study." (PMID 33075095, 2020). "The observed reduction in IL10RB levels associated with increased physical activity suggests that physical activity may modulate IL-10 signaling pathways, potentially enhancing anti-tumor immune responses." (PMID 39769247, 2024). "Consistent with IL22RA1, higher expression of IL10RB, IL10RA and IL20RB in tumor tissues was associated with worse survival in patients." (PMID 35874683, 2022). "Through transduction of IL10-induced signaling, IL10RB (IL10 receptor subunit beta) contributes to the immunosuppressive tumor microenvironment." (PMID 35681785, 2022). "In these immunosuppressive marker genes, TGFB1, NECTIN2, LGALS9, LAG3, and IL10RB were significantly correlated with CCDC137 expression in most tumor types." (PMID 34055889, 2021). "These experiments showed that the Il10rb−/− CD103+ cDC1 vaccine suppressed bilateral tumor growth effectively, and to a similar degree as that observed upon vaccination with Stat3∆/∆ CD103+ cDC1s." (PMID 31947933, 2020). "Stat3∆/∆ CD103+ cDC1- or Il10rb−/− CD103+ cDC1-vaccinated mice exhibited delayed bilateral tumor growth and increased survival, compared to mice vaccinated with Stat3fl/fl CD103+ cDC1s." (PMID 31947933, 2020). "The presence of IL10RB/IL20RA in tissue was associated with shorter survival time, compatible with the notion that IL26 signaling per se contributes to tumor progression." (PMID 31948053, 2020). "Not only does IL-1B appear positively correlated with MAP17 in all tumors, other interleukins including IL-15, IL-18, IL-1A, IL-32 and IL-7 and interleukin receptors including IL-10RB, IL-17RC and IL-2RG appear in at least three of the tumor types." (PMID 29228712, 2017). "By reducing IL10RB levels, physical activity may limit IL-10-driven immunosuppressive signaling, thereby shifting the tumor microenvironment towards a state more conducive to effective anti-tumor immunity." (PMID 39769247, 2024). "Our results suggest that mutations that disrupt the interactions of IL-10 with its receptors (IL-10RA and IL-10RB) and α2-macroglobulin (A2M) may enhance inflammation and modulate anti-tumor immunity." (PMID 25056661, 2014). "Therefore, decreased IL10RB expression may enhance immune surveillance by diminishing IL-10-mediated immunosuppression in the tumor microenvironment." (PMID 39769247, 2024). "According to this study, PTK6 expression was positively correlated with CD160, IL10RB, and PVRL2 while being negatively correlated with ADORA2A, BTLA, CSF1R, and KDR in the other tumor types." (PMID 38573548, 2024). "A total of 30 IL22RA1-correlated genes (e.g. IL17D, IL22RA2, IL20RB, IL10RA, IL10RB, TSLP and TYK2) are involved in the JAK/STAT pathway which promotes tumor progression." (PMID 35874683, 2022). "More importantly, FOLR2+ TAMs significantly expressed typical immunosuppressive genes including TGFB1, TGBR1, IL10, and IL10RB, validating the immunosuppressive role of FOLR2+ TAMs in the HCC tumor niche." (PMID 36238304, 2022). "To this end, we first investigated both IL10RA and IL10RB and its downstream targets JAK1 and TYK2 gene expression levels in 370 HCC tumor samples using the publicly available The Cancer Genome Atlas (TCGA) dataset." (PMID 32443546, 2020). "While IL10RB is widely expressed on hematopoietic cells, IL20RA usually occurs only in activated immune cells; expression of both receptors on tumor cell lines and tissues has been described." (PMID 31948053, 2020). "Furthermore, the present study found a strong correlation between the expression of target genes (IL10RB, INHBB, NEO1, PIK3R1, BCL2, ID4, and INHBA) and the infiltration of tumor-killing cells into the tumor immune microenvironment in HNC." (PMID 40647469, 2025).
tumor (continued). "Additionally, a differential expression of the cytokine genes CCL2, CCL20, TGFB1, and TGFB2; the transcription factor gene IRF4; and the receptor genes CCR2, IL10RB, TGFBR1, and TGFBR2 was identified in tumor tissue and vestibular nerve tissue." (PMID 39272860, 2024). "Interestingly, we found their receptors, IL17RA/IL17RC for IL17A/IL17F, IL10RB/IL22RA1 for IL22, and IL20RA/IL10RB for IL26, were upregulated in tumor cell than in normal epithelial cells." (PMID 35999201, 2022). "Moreover, the positive correlations between CCDC137 expression and immunosuppressive genes, such as TGFB1, NECTIN2, LGALS9, LAG3, and IL10RB, indicate the key role of CCDC137 in regulating tumor immunology, macrophage polarization, and CAFs formation." (PMID 34055889, 2021). "As non-vaccinated tumors also responded to the Stat3∆/∆ or Il10rb−/− CD103+ cDC1 vaccine, this indicates promotion of systemic anti-tumor immunity." (PMID 31947933, 2020).
cancer (22 papers, 2014 to 2025). A tumor composed of atypical neoplastic, often pleomorphic cells that invade other tissues. "The IL-6R, IL-8, IL-10RB, IL-12A, and IL-12B was associated with the prognosis of cancer in data of both our study and a previous study." (PMID 25075970, 2014). "Among them, IL-6R, IL-8, IL-10RB, IL-12A, and IL-12B was significantly associated with the prognosis of cancer consistent to our finding." (PMID 25075970, 2014). "In the other types of cancer studies, IL-6R, IL-8, IL-10RB, IL-12A, and IL-12B genes were consistently associated with cancer prognosis between our study and theirs." (PMID 25075970, 2014). "The identification of IL10RB as a partial mediator highlights the role of immune modulation in the anti-cancer effects of physical activity." (PMID 39769247, 2024). "A six-biomarker model (HE4, CA125, CXCL1, ITGAV, CEACAM1, IL-10RB and age) was the best model for discrimination between benign tumors and borderline tumors + cancer, with AUC 0.868 and sensitivity 0.86 / specificity 0.82 at best point cut-off (p = 0.016)." (PMID 33075095, 2020). "Strikingly, ACACA expression exhibited significant negative correlations with the immune checkpoint-related genes (PDCD1, LAG3, LAGLS9, IDO1, CD244, CTLA4 and TIGIT), while showing positive associations with other genes (TGFBR1, KDR, IL10RB, CD160 and CD274) across most cancer types." (PMID 41169354, 2025). "In the current study, the plasma levels of IL-10RB were higher in patients with cancer." (PMID 33075095, 2020). "To explore similar mechanisms in other cancers, we conducted a correlation analysis of CD59 with macrophage, IL10, IL10RB, IL6, and IL6R on KIRC, CESC, GBM, HNSC, and STAD." (PMID 39518137, 2024). "In the present study, our analysis has shown that CD276 expression was positively correlated with a number of immune checkpoint genes, including TGFBR1, TGFB1, NECTIN2, IL10RB and CSF1R, in most types of cancer." (PMID 36717836, 2023). "Our analysis revealed a significant correlation (p < 0.05 between DNMT1 and ADORA2A, IL10RB, and CTLA-4 in certain cancers." (PMID 37628671, 2023). "In a few cancers (particularly TCGT), CDKN2C expression was related to multiple immune-related genes, including TMEM173 (an immunostimulator), IL10RB (an immunoinhibitory), and TAPBP (a major histocompatibility complex molecule) in TGCT." (PMID 35751045, 2022). "Concerning immune inhibitors, AURKA displayed a positive correlation with IL10RB in most cancers but a negative correlation in COAD." (PMID 37965456, 2023). "The best performing model for discrimination between benign tumors and borderline tumors + cancer was a 6-biomarker combination (HE4, CA125, ITGAV, CXCL1, CEACAM1, IL-10RB) and age (AUC 0.868, sensitivity 0.86 and specificity 0.82, p = 0.016 for comparison with the reference model)." (PMID 33075095, 2020).
infection (14 papers, 2015 to 2025). The state of being infected such as from the introduction of a foreign agent such as serum, vaccine, antigenic substance or organism. "The protein expression of three proteins (IL-17C, IL-18, and IL-10RB) was significantly decreased in caspase-1-deficient cells compared to Cas9 cells following HK1651 infection." (PMID 40137780, 2025). "Using single-cell RNA-sequencing (scRNA-seq), we measured the expression of either type I (Ifnar1 and Ifnar2) or type III (Ifnlr1 and Il10rb) IFN receptor subunits in mouse lung cells on day 1 post-infection." (PMID 38530032, 2024). "Several cytokine response elements including STAT5B, STAT6, and IL10RB contributed to enrichment of a number of pathways relating to response to infection." (PMID 34658838, 2021). "Of note, only small changes in expression of Il10rb were observed between days 0 and 7, whereas Ifnlr1 mRNA was time-dependent, with the highest expression occurring on days 1 and 4 after infection." (PMID 30655513, 2019). "Moreover, Isg12+Cst7+ neutrophils expressed Cd274 and Il10rb, potentially interacted with activated cytotoxic T cells and Slamf9+ macrophages, and jointly established the favoring niches for the resolution of inflammation at the late stage of infection." (PMID 39414783, 2024). "In the same study, infection of moMΦ with Georgia 2007 strain down-regulated other receptors, such as interferon receptors (IFNAR1, IFNAR2, IFNGR) and interleukin receptors (IL4R, IL10RA, IL10RB, and IL17RA), as well as transcriptomic factors (e.g., FOS, JUN, and TBK1)." (PMID 40530033, 2025). "To explore whether SECoVs infection affects IFN receptors expression, we next compared the receptor expression of the three types of IFNs, including type I IFN receptors (IFNAR1 and IFNAR2), type II IFN receptors (IFNGR1 and IFNGR2), and type III IFN receptors (IL10RB and IFNLR1)." (PMID 35126380, 2021).
cardiovascular diseases (4 papers, 2020 to 2025). "Such efforts would provide stronger evidence for the role of IL10RB and other cytokines in cardiovascular disease prevention, offering valuable targets for future therapeutic strategies." (PMID 40429759, 2025). "Targeting IL10RB could amplify these effects, offering a potential strategy to complement physical activity in preventing and treating cardiovascular diseases." (PMID 40429759, 2025). "In cardiovascular diseases, the genes FBRSL1, IL10RB, ACE2 and ABO were those that were outstanding." (PMID 36430729, 2022).
benign tumors (3 papers, 2020 to 2024). "Mediation analysis identified interleukin-10 receptor subunit β (IL10RB) as a partial mediator, accounting for 5.95% of the protective effect on benign tumors." (PMID 39769247, 2024). "A 6-biomarker model (HE4, CA125, CXCL1, ITGAV, CEACAM1, IL-10RB and age) was found to be the best model for discrimination between benign tumors and EOC including borderline tumors." (PMID 33075095, 2020). "Adenosine deaminase levels, interleukin-10 receptor subunit beta expression, tumor necrosis factor (TNF)-related apoptosis-inducing ligand levels, and TNF-related activation-induced cytokine levels showed a causal relationship with thymic benign tumors, which are its risk factors." (PMID 38828408, 2024).
inflammation (2 papers, 2017 to 2021). Aberrant reaction of the microcirculation characterized by movement of fluid and leukocytes from the blood into extravascular tissues. "To explore the potential mechanisms of IL-22 which inhibited the OVA-induced airway inflammation, we performed immunohistochemistry to detect the expression of functional IL-22 receptor, a heterodimer of IL-22RA1 and IL-10RB, and its soluble binding protein, IL-22BP." (PMID 34836520, 2021).
IL10RB also shares sentences with these, for which no sentence is quoted: colorectal (3 papers); asthma (2); B-cell lymphoma (2); liver diseases (2); liver fibrosis (2); lung carcinoma (2); narcolepsy (2); respiratory failure (2); steatosis (2); type 1 diabetes (2); adult T-cell leukemia/lymphoma (1); alcohol-induced acute pancreatitis (1); ampulla of Vater carcinoma (1); Anosmia (1); antisocial/borderline personality disorder (1); autosomal recessive disease (1); behavioral disorders (1); cholangitis (1); Cholecystitis (1); cholelithiasis (1); chronic myeloid leukemia (1); chronic) renal failure (1); colon cancer (1); congestive heart failure (1); cystitis (1); dementia (1); depression (1); endothelial dysfunction (1); fibrosarcoma (1); head and neck squamous cell carcinoma (1).
A further 42 diseases each share a sentence with IL10RB in 1 paper.